FXYD4 (FXYD domain containing ion transport regulator 4)
Description:
Associates with and regulates the activity of the sodium/potassium-transporting ATPase (NKA) which catalyzes the hydrolysis of ATP coupled with the exchange of Na(+) and K(+) ions across the plasma membrane (By similarity). Increases the apparent affinity of the transporter for Na(+) and increases NKA activity (By similarity).
Synonyms: CHIF
Tractability: Antibody: its Gene Ontology location is reachable by antibodies, with high confidence; UniProt places it where antibodies can reach, with medium confidence; UniProt predicts a signal peptide or a membrane-spanning region.
Gene: Protein-coding gene on chromosome 10 (43,371,635 to 43,376,335, forward strand). Ensembl gene ENSG00000150201.
Subcellular location: Cell membrane; Basolateral cell membrane
Subcellular location (Human Protein Atlas): Cytosol
Pathways (Reactome):
Disease: Potential therapeutics for SARS
Muscle contraction: Ion homeostasis
Transport of small molecules: Ion transport by P-type ATPases
Gene Ontology:
Molecular function: sodium channel regulator activity; ATPase binding; ion channel regulator activity
Biological process: establishment or maintenance of transmembrane electrochemical gradient; intracellular potassium ion homeostasis; intracellular sodium ion homeostasis; positive regulation of sodium ion export across plasma membrane; potassium ion import across plasma membrane; proton transmembrane transport; sodium ion export across plasma membrane; potassium ion transmembrane transport; regulation of monoatomic ion transport
Cellular component: sodium:potassium-exchanging ATPase complex; basolateral plasma membrane; plasma membrane; membrane
Genetic constraint (gnomAD): Loss-of-function variants: 13 observed, 18.78 expected, observed/expected ratio (o/e) 0.69, 90% interval 0.45 to 1.1. The upper end of that interval is the gene's LOEUF score, 1.1, which puts it in group 4 of 6, group 1 being the genes least tolerant of losing a copy. Missense variants: 86 observed, 98.75 expected, observed/expected ratio (o/e) 0.87, 90% interval 0.73 to 1.04. Synonymous variants: 33 observed, 36.22 expected, observed/expected ratio (o/e) 0.91, 90% interval 0.69 to 1.22.
Homologues: Orthologues: chimpanzee FXYD4 (99% identical), macaque FXYD4 (93% identical), dog FXYD4 (72% identical), mouse Fxyd4 (67% identical), rabbit FXYD4 (64% identical), rat Fxyd4 (60% identical), tropical clawed frog fxyd3 (42% identical). Paralogues in human: FXYD3 (54% identical), FXYD6 (35% identical), FXYD1 (29% identical), FXYD5 (26% identical), FXYD7 (24% identical), FXYD2 (22% identical).
Diseases named in the same sentence as FXYD4 in open-access papers:
FXYD4 is named in the same sentence as 10 diseases in open-access papers, as found by Europe PMC text mining. Sharing a sentence is not in itself a finding about the gene and the disease. The quoted sentences say what the papers report.
acute kidney injury (1 paper, 2023). Sudden and sustained deterioration of the kidney function characterized by decreased glomerular filtration rate, increased serum creatinine or oliguria. "Acute kidney injury was associated with weak expression of Fxyd4, but the significance of this has not been investigated." (PMID 37895006, 2023).
angiosarcoma (1 paper, 2016). A malignant tumor arising from the endothelial cells of the blood vessels. "Most interestingly, expression of FXYD2 and FXYD4 genes is modified in angiosarcoma vs control human samples." (PMID 27716384, 2016).
colon cancer (1 paper, 2021). "The expression of FXYD2, FXYD3 and FXYD4 is an independent prognostic factor for for the survival of colon cancer." (PMID 34753441, 2021).
Sepsis (1 paper, 2023). Sepsis is defined as life-threatening organ dysfunction caused by a dysregulated host response to infection. "Fxyd4 is elevated in sepsis, but mitochondrial transplantation decreases it." (PMID 37895006, 2023). "Using SHAM expression levels as another control variable, we further identified six genes (Fxyd4, Apex2l1, Kctd4, 7SK, SNORD94, and SNORA53) that were highly expressed after sepsis induction and observed that their expression levels were attenuated by mitochondrial transplantation." (PMID 37895006, 2023).
cancer (2 papers, 2021 to 2023). A tumor composed of atypical neoplastic, often pleomorphic cells that invade other tissues. "With limited research on the role of FXYD4 in cancer progression, we noticed that FXYD4 was physiologically expressed in the distal colon and kidney." (PMID 34270462, 2021). "FXYD1, FXYD3, FXYD6 and FXYD7 were significantly downregulated in cancer samples, while FXYD4 and FXYD5 were markedly overexpressed." (PMID 34270462, 2021).
FXYD4 also shares sentences with these, for which no sentence is quoted: breast carcinoma (1 paper); colitis (1); colorectal cancer (1); head and neck cancer (1); tumour (1).